PTH (parathyroid hormone)
Diseases named in the same sentence as PTH in open-access papers (continued):
Sharing a sentence is not in itself a finding about the gene and the disease.
pseudopseudohypoparathyroidism (15 papers, 2012 to 2025). A disease characterized by a constellation of clinical features collectively termed Albright hereditary osteodystrophy (AHO) but no evidence of resistance to parathyroid hormone (PTH), which is seen in other forms of pseudohypoparathyroidism (PHP). "Genetic defects affecting GNAS can cause several human diseases such as Pseudopseudo hypoparathyroidism (PHP, MIM:612462, 603233, 103580 ), end-organ resistance to parathyroid hormone (PTH, MIM: 612463), progressive osseous heteroplasia (POH, MIM: 166350)." (PMID 39285472, 2024). "PHP is classified into five types (PHP1A, PHP1B, PHP1C, PHP2, and Pseudopseudohypoparathyroidism (PPHP)) based on phenotype, hormone resistance profile, cAMP response to exogenous PTH, and Gsα protein activity." (PMID 41170251, 2025). "PHP is classified into three types based on the defect molecular in the PTH signal transduction pathway, which are named as PHP-1, PHP-2 and pseudopseudohypoparathyroidism (PPHP)." (PMID 33422028, 2021). "Interestingly, if the GNAS mutation is instead derived from the male, there is no resistance to PTH actions in the kidney, but only the skeletal abnormalities, which is known as pseudopseudo-hypoparathyroidism (PPHP)." (PMID 36246903, 2022).
hypogonadism (14 papers, 2010 to 2025). A disorder characterized by decreased function of the gonads. "Additional causes that could be related to bone loss in such patients (ie, GH deficiency, hypogonadism, longstanding elevated PTH levels) should be treated as well." (PMID 40177730, 2025). "In these patients, bone loss might occur as a result of untreated hypogonadism, long-term excess levels of PTH, GH deficiency and/or the onset of physiological menopause." (PMID 29959430, 2018). "Bone loss could be attributed to other endocrine dysfunctions such as hypercortisolism, hypogonadism, and GH deficiency caused by pituitary mass counteracting the anabolic effect of PTH on trabecular bone." (PMID 27846313, 2016). "PTH and 25(OH)D levels were similar between patients with active disease/controlled disease and patients with hypogonadism/normal gonadal status." (PMID 35340319, 2022). "Of the five patients evaluated for hypogonadism, one had gonadotropin resistance together with PTH and TSH resistance." (PMID 21274345, 2010). "Age, eGFR, ALP, calcium, and CTX were increased in acromegalic patients with hypogonadism compared in those without hypogonadism (p<0.001, p=0.004, p=0.003, p=0.001, and p=0.009, respectively) while phosphorus, PTH, and 25(OH)D levels were similar between the two groups." (PMID 35340319, 2022).
osteonecrosis (14 papers, 2015 to 2025). A none disease characterized by death of bone tissue due to a lack of blood supply. "Keskinruzgar also reported the risk of osteonecrosis development may decrease when PTH is administered before or immediately after tooth extraction." (PMID 33420145, 2021). "Using different rodent models of osteonecrosis and PTH, other studies have reported an improvement in prevalence of osteonecrosis with a combination treatment of core decompression and PTH, including improvement in neovascularization." (PMID 31903130, 2020). "Our data showed homogeneous high signal intensity areas in T1W images and lower intensity signal in T2-weight images, thus demonstrating the positive efficacy of PTH on osteonecrosis." (PMID 28562696, 2017). "Recently, parathyroid hormone therapy was administered to patients with intravertebral osteonecrosis." (PMID 27595101, 2016). "After the treatment of 4 weeks, the LPS/MPS + PTH group showed significant lower incidence rate of osteonecrosis compared with the LPS/MPS + NS group (16.7 % vs.75 %, P < 0.05)." (PMID 26163144, 2015). "This validated that PTH could enhance bone repair and decrease the occurrence of osteonecrosis, which might reduce the incidence of fracture after CD." (PMID 28562696, 2017). "All the rats were randomized into 4 groups: 18 rats from LPS/MPS group, LPS/MPS + PTH group and LPS/MPS + NS group were given lipopolysaccharide (20 μg/kg) and methylprednisolone (40 mg/kg) to establish the steroid induced osteonecrosis model." (PMID 26163144, 2015). "By the HE stained histological examination, the incidence of osteonecrosis was 75 %(9/12) in the LPS/MPS + NS group and 16.7 %(2/12) in the LPS/MPS + PTH group at 8 weeks." (PMID 26163144, 2015). "At 8 weeks, the incidence of osteonecrosis was 50 %(6/12) in the LPS/MPS + NS group and 0(0/12) in the LPS/MPS + PTH group(P < 0.05)." (PMID 26163144, 2015). "A further three articles obtained contradictory results with regard to PTH as a predictive value of osteonecrosis but failed to contemplate vitamin D and calcium supplements in control cases." (PMID 26827062, 2016). "Osteonecrosis development was, however, not blocked by teriparatide treatment (Ale + PTH) but rather developed at levels comparable to those seen in mice not treated with teriparatide (Ale), suggesting that SSBT in this context does not promote osteonecrosis development." (PMID 28387378, 2017).
pancreatitis (14 papers, 2016 to 2025). Inflammation of the pancreas. "Parathyroid hormone is thought to play a role in the pathogenesis of pancreatitis by inhibiting pancreatic vascularisation or by causing the formation of micro thrombi leading to necrosis of the pancreatic parenchyma." (PMID 36582902, 2022). "The connection between high PTH concentration in addition to consecutive elevated serum calcium and pancreatitis was first established by Cope in 1957 who published two cases; however, the first such case dates from 1903 (this was a postmortem diagnosis)." (PMID 38928056, 2024). "As a practical point, identifying an elevated blood calcium level at the moment of pancreatitis diagnosis requires an additional PTH assessment." (PMID 38928056, 2024). "After parathyroidectomy, the patient had no more pancreatitis, and all the biochemical markers, including PTH and calcium, were within normal range." (PMID 41001160, 2025). "Other signs are elevation of serum PTH concentrations, neck mass (34%–52%), bone (34%–73%) and renal disease (32%–70%), pancreatitis (0%–15%), no symptoms (2%–7%), and symptoms of local and adjacent structure invasion in case of a not functioning PC (rare form)." (PMID 37397577, 2023). "The direct toxic action of PTH on the pancreas is mentioned, but pancreatitis is not usually found in dialysis patients with elevated PTH, and PTH is not higher in patients with pancreatitis in the course of PHPT." (PMID 27774509, 2016). "PTH in patients with pancreatitis on PHPT is not higher than among those with only PHPT." (PMID 27774509, 2016).
pseudohypoparathyroidism type 1B (14 papers, 2011 to 2026). Pseudohypoparathyroidism type 1B (PHP-1b) is a type of pseudohypoparathyroidism (PHP) characterized by localized resistance to parathyroid hormone (PTH) mainly in the renal tissues which manifests with hypocalcemia, hyperphosphatemia and elevated PTH levels. "When the methylation pattern is affected, it causes pseudohypoparathyroidism type 1B (PHP1B) or inactivating PTH/PTHrP signaling disorder 3 (iPPSD3)." (PMID 39736869, 2024). "Pseudohypoparathyroidism type 1B (PHP1B), caused by abnormal methylation of the GNAS gene leading to parathyroid hormone (PTH) resistance, lacks Albright hereditary osteodystrophy features and is often misdiagnosed." (PMID 40893942, 2025). "Pseudohypoparathyroidism type 1b (PHP-1b) is a rare genetic disorder caused by mutations or epigenetic alterations of the maternal GNAS gene, resulting in isolated renal resistance to parathyroid hormone (PTH) and, in some cases, partial resistance to thyroid-stimulating hormone." (PMID 41884215, 2026). "Pseudohypoparathyroidism type 1b does not involve skeletal symptoms but does resistance to PTH and TSH; and urinary cAMP increases after PTH administration, though phosphaturia does not occur." (PMID 31320908, 2019). "Pseudohypoparathyroidism type 1B (PHP1B; MIM#603233) is a rare imprinting disorder (ID), associated with the GNAS locus, characterized by parathyroid hormone (PTH) resistance in the absence of other endocrine or physical abnormalities." (PMID 29445425, 2018). "Pseudohypoparathyroidism type 1B (PHP1B; MIM # 603233) is a rare imprinting disorder (ID) characterized by renal resistance to parathyroid hormone (PTH) in the absence of other endocrine or physical abnormalities." (PMID 29445425, 2018).
Cachexia (13 papers, 2018 to 2026). Severe weight loss, wasting of muscle, loss of appetite, and general debility related to a chronic disease. "To exclude the effects of PTH in CKD-associated cachexia in our experiment, we will need to perform parathyroidectomy in mice, but this is beyond the scope of the study." (PMID 32843714, 2020). "Similarly, PTH was found to indirectly trigger muscle loss by affecting adipose tissue in cachexia models associated with CKD and cancer." (PMID 40731865, 2025). "For example, the effect of PTH on fat and muscle cells causes cachexia in patients with CKD15." (PMID 30692566, 2019). "In fact, these data corroborate new theories, already highlighted by other authors in the literature, in which PTH seems to play a central role in the cachexia genesis." (PMID 39554503, 2024). "The 5/6 nephrectomy mice with elevated PTH level experienced cachexia, reduced body weight and increased energy expenditure." (PMID 37484844, 2023). "Parathyroid-hormone (PTH) and Parathyroid-hormone-related protein (PTHrP) have been implicated in the browning of WAT in cachexia." (PMID 28677104, 2018). "In vitro studies indicate that extracellular calcium suppresses thermogenic gene expression and impairs brown adipocyte differentiation, while elevated PTH can enhance BAT thermogenesis, as seen in cachexia models." (PMID 40429675, 2025). "CKD mice in this study had elevated circulating PTH levels but anakinra did not normalize serum PTH levels in CKD mice, suggesting that PTH/PTHrP pathway may not be the only mediator of crosstalk between adipose tissue and muscle in CKD-associated cachexia." (PMID 34302016, 2021).
cerebrovascular disease (13 papers, 2013 to 2025). "In examining the association between serum PTH levels and cerebrovascular disease, as well as the contribution of 25(OH)D, this study made some important conclusions." (PMID 28115793, 2017). "Previous clinical studies on the role of PTH on cerebrovascular diseases have shown mixed results." (PMID 41050279, 2025). "High-level PTH may play a role in cognitive dysfunction and cerebrovascular diseases by way of PTH2 receptors (PTHrP) scattered throughout the arteries of the cerebral cortex." (PMID 37923800, 2023). "The clinical characteristics of participants with cerebrovascular disease were very similar to participants without cerebrovascular disease, except for age and PTH." (PMID 30791885, 2019). "In the extensively adjusted model, greater odds of non-adherence were observed for patients with higher PTH levels and cerebrovascular disease." (PMID 24090377, 2013).
hyperlipidemia (13 papers, 2014 to 2025). "The decrease in bone density is most likely a result of hyperlipidemia, which we found previously to reduce skeletal bone density, apparently overriding the anabolic effects of parathyroid hormone, which we previously found to be upregulated with exercise." (PMID 40252010, 2025). "Biochemical analysis of mice serum in hyperlipidemia mice displayed augmented levels of parathyroid hormone (PTH), tumor necrosis factor-α (TNF-α), C-terminal telopeptide of type-1 collagen (CTX; a bone resorption marker), calcium, and phosphorus." (PMID 27338453, 2016). "The correlation of high PTH concentration and hyperlipidemia have only been observed in PHPT population, while in PHP1, the defected GPCR pathway may be a concerning factor for the non-responding GPCR-dependent lipolysis pathway of PTH." (PMID 38017461, 2023).
thyroid nodule (13 papers, 2012 to 2025). A small circumscribed mass in the THYROID GLAND that can be of neoplastic growth or non-neoplastic abnormality. "We report a case of a 24-year-old male patient who presented with a nontraumatic humeral fracture and generalized fatigue and was found to have a calcium level of 16.9 mg/dL, PTH level of 3,164 pg/mL, and a 2.9 cm right inferior thyroid nodule." (PMID 40342445, 2025). "Further, fine needle aspiration parathyroid hormone (PTH) wash-out from that thyroid nodule showed very high PTH levels, referring to the thyroid's EPA." (PMID 40190965, 2025). "In cases with suspicious thyroid nodules or parathyroid glands, and markedly elevated parathyroid hormone and serum calcium levels, the coexistence of PC should be considered." (PMID 39054438, 2024). "Preoperative parathyroid hormone and serum calcium testing are recommended for patients with solid thyroid nodules (Bethesda IV–V)." (PMID 37183888, 2023). "The discrepancies reported relate to both differences in technique and patient cohorts, as Sestamibi uptake is influenced by PTH levels and the presence, or absence, of thyroid nodules." (PMID 23758620, 2013). "Furthermore, fine-needle aspiration biopsy (FNAB) with a PTH assay on needle lavage fluid was performed in one case to differentiate between the suspected functional PA and a thyroid nodule." (PMID 39768933, 2024). "The present study detected PTH levels in all non-parathyroid lesions (benign-malignant thyroid nodules and lymph nodes), as proven by cytological or histopathological examination." (PMID 37745742, 2023). "PTH-WO levels (median (IQR)) were significantly higher in the positive group (n = 93, 5000 (IQR: 1600) ng/L), compared to the negative group (n = 11, 17.0 (IQR: 13.1) ng/L) and concomitant thyroid nodule aspirate groups (n = 30, 14.0 (IQR: 4.3) ng/L) (p < 0.001)." (PMID 37745742, 2023). "PTH-WO levels (median (IQR)) were significantly higher in the positive group (n = 93, 5000 (1600) ng/L) compared to the negative group (n = 11, 17 (13.1) ng/L) and thyroid nodule aspirate group (n = 30, 14 (4.3) ng/L) (p < 0.001)." (PMID 37745742, 2023).
urolithiasis (13 papers, 2011 to 2025). Stone(s) within the urinary tract. "For patients with recurrent urinary stones, we recommend measuring blood calcium and PTH, and if there are abnormalities, screening other endocrine glands to exclude the possibility of MEN1." (PMID 40421248, 2025). "For patients with recurrent urinary stones, we recommend measuring blood calcium and PTH, and if there is an abnormality, screening other endocrine glands to exclude MEN1." (PMID 40421248, 2025). "Donors in both groups had detailed preoperative investigations for urolithiasis which included serum biochemical analysis (ionized calcium, uric acid, parathyroid hormone levels, and creatinine) and urinary electrolyte analysis." (PMID 22084792, 2011). "Due to elevated PTH in severe CP patients, which possibly brings hypercalcemia and clinical symptoms such as urolithiasis, we hypothesize that CP can potentially induce urolithiasis." (PMID 30083446, 2018). "We compared the patients’ characteristics, urinary specific gravity, urine pH, serum calcium and intact parathyroid hormone in the urolithiasis and non-urolithiasis groups." (PMID 33899133, 2021). "However, there was no causal association between other common risk factors (PTH, CRP, IL6, IL18, IL27, IL8, IL16, IL1Ra, coffee consumption, age of smoking initiation, smoking initiation, and cigarettes smoked per day) and urolithiasis in the meta-analysis." (PMID 37624788, 2023).
tuberculosis (12 papers, 2019 to 2025). A chronic, recurrent infection caused by the bacterium Mycobacterium tuberculosis. "Additionally, the metabolites associated with Tuberculosis and the Parathyroid hormone synthesis, secretion, and action are both 25-Hydroxycholecalciferol." (PMID 41199947, 2025). "In addition, prior exposure to PTH may be associated with the increased frequency of INH-resistant tuberculosis strains with inhA mutations in China." (PMID 31382930, 2019). "Arranged in order of increasing P-values, these are: Steroid biosynthesis, Antineoplastics-alkylating agents, Tryptophan metabolism, Parathyroid hormone synthesis, secretion, and action and Tuberculosis." (PMID 41199947, 2025). "Then, these significant metabolites were observed to be notably enriched in four distinct metabolic pathways, namely, “purine metabolism”; “parathyroid hormone synthesis, secretion and action”; “choline metabolism in cancer”; and “tuberculosis”." (PMID 38962681, 2024). "The diagnosis of tuberculosis was made some months after KTx (PTH levels were already normal)." (PMID 33909856, 2021).
autoimmune disease (11 papers, 2015 to 2026). A disorder resulting from loss of function or tissue destruction of an organ or multiple organs, arising from humoral or cellular immune responses of the individual to their own tissue constituents. "PTH1R expression was found to be significantly higher in B-lymphocytes in SLE and pSS patients than in healthy controls, suggesting that PTH may activate B cells in patients with autoimmune diseases." (PMID 37841984, 2023). "Vitamin D and its metabolites are not only involved in endocrine interactions among the kidney, bone, and parathyroid hormone but also in immunity, blood pressure, muscular function, T-cell regulation, antioxidative defence via glutathione metabolism, autoimmune disease, autism, and cancer defence." (PMID 35892685, 2022). "Parathyroid hormone level in serum remains the key information for Vitamin D3 dose finding concepts in autoimmune disease as long as there is no better information about individual factors determining vitamin D responsiveness available." (PMID 33897704, 2021). "However, DS patients with a history of autoimmune diseases showed higher PTH levels (56.70 ± 11.98 pg/mL) than patients without a history of autoimmune diseases (35.37 ± 7.51 pg/mL; P < 0.05)." (PMID 25685147, 2015). "Finally, we did not evaluate PTH, which is usually increased in autoimmune diseases." (PMID 36364863, 2022).